CASP12 (caspase 12 (gene/pseudogene))
Description:
May function as a negative regulator of inflammatory responses and innate immunity. May reduce cytokine release in response to bacterial lipopolysaccharide during infection. Reduces activation of NF-kappa-B in response to TNF. May lack protease activity (Probable).
Synonyms: formerly CASP12P1
Tractability: Small molecule: a drug acting on it is in phase 2 or 3 trials. PROTAC: a small molecule that binds it is known.
Gene: Protein-coding gene on chromosome 11 (104,885,718 to 104,898,670, reverse strand). Ensembl gene ENSG00000204403.
Gene Ontology:
Molecular function: cysteine-type endopeptidase activity; cysteine-type peptidase activity
Biological process: apoptotic process; positive regulation of inflammatory response; positive regulation of neuron apoptotic process; proteolysis; regulation of apoptotic process
Cellular component: endoplasmic reticulum; cytoplasm; cytosol; NLRP1 inflammasome complex
Genetic constraint (gnomAD): Missense variants: 162 observed, 165.91 expected, observed/expected ratio (o/e) 0.98, 90% interval 0.86 to 1.11. Synonymous variants: 55 observed, 58.38 expected, observed/expected ratio (o/e) 0.94, 90% interval 0.76 to 1.18.
Homologues: Orthologues: chimpanzee CASP12 (98% identical), macaque CASP12 (72% identical), dog CASP12 (61% identical), guinea pig CASP12 (61% identical), rat Casp12 (59% identical), mouse Casp12 (59% identical), Caenorhabditis elegans ced-3 (23% identical), zebrafish casp8 (21% identical), Caenorhabditis elegans csp-1 (19% identical), Drosophila melanogaster Dronc (18% identical), Caenorhabditis elegans csp-2 (18% identical), Drosophila melanogaster Decay (17% identical), and 3 more. Paralogues in human: CASP4 (51% identical), CASP5 (48% identical), CASP1 (45% identical), CASP2 (23% identical), CASP9 (23% identical), CASP3 (22% identical), CASP8 (20% identical), CASP10 (20% identical), CASP7 (20% identical), CASP6 (17% identical), CASP14 (16% identical), CFLAR (15% identical), and 4 more.
Diseases named in the same sentence as CASP12 in open-access papers:
CASP12 is named in the same sentence as 34 diseases in open-access papers, as found by Europe PMC text mining. Sharing a sentence is not in itself a finding about the gene and the disease. The quoted sentences say what the papers report.
Sepsis (5 papers, 2008 to 2024). Sepsis is defined as life-threatening organ dysfunction caused by a dysregulated host response to infection. "For example, a stop codon mutation in CASP12 in certain human populations was likely selected for a decreased risk for sepsis and a frameshifting deletion in the chemokine receptor gene CCR5 protects humans from HIV infection." (PMID 33575564, 2020). "Interestingly, it has been argued that the inactivation of CASP12 in humans might be protective against infection and sepsis, with the increase in LoF allele frequency being driven by positive selection." (PMID 39488654, 2024). "Indeed, signatures of natural selection have been reported at another human locus, namely CASP12, as a possible adaptive response to sepsis." (PMID 18817538, 2008).
melanoma (3 papers, 2019 to 2021). A malignant, usually aggressive tumor composed of atypical, neoplastic melanocytes. "Our results showed that, similarly to STK26 and KCNT2, the transcription of CASP12 in melanoma was reduced relative to nevus, which might mediate the process of the conversion of nevus to melanoma." (PMID 31557882, 2019). "Unfortunately, there were no IHC results of Casp12 in the Human Protein Atlas database, so we could not analyze the difference in the protein expressions of CASP12 between nevus and melanoma, which is worth further investigation." (PMID 31557882, 2019).
hepatoma (2 papers, 2019 to 2020). "The ethyl acetate extract of A. camphorata was shown to induce the activation of calpain-3 (CAPN-3) and caspases-12 (CASP-12) by increasing the level of Ca2+ in the cytoplasm of Hep3B cells and further induced the apoptosis of hepatoma cells." (PMID 32932919, 2020).
nasopharyngeal carcinoma (2 papers, 2019). A carcinoma arising from the nasopharyngeal epithelium. "Similarly, the Casp12 degraded IκBα protein and enhanced MMP-9 expression in human nasopharyngeal carcinoma (hNC) cell invasion." (PMID 31557882, 2019).
age-related hearing loss (1 paper, 2023). "In a mouse model of age-related hearing loss, morphological alterations in the cochlea were concomitant with an increase in ER stress markers and the ER stress-related apoptotic proteins, including Casp12 and the transcription factor CHOP." (PMID 37108509, 2023).
colitis (1 paper, 2015). Inflammation of the colon. "Casp12 encodes an inflammatory caspase that has been shown to be involved in the pathogenesis of both experimental colitis and colitis‐associated cancer models 18, whilst Tnfs10 encodes the TNF family ligand TRAIL, which signals through the classical NF‐κB pathway." (PMID 25727407, 2015).
colon carcinoma (1 paper, 2019). "In vitro experiments showed that Casp12-deficient mice were more sensitive to drug-induced colon cancer." (PMID 31557882, 2019).
COVID-19 (1 paper, 2023). A disease caused by infection with severe acute respiratory syndrome coronavirus 2. "The current population-based study implies the potential value of CASP-12 in predicting the prognosis of COVID-19." (PMID 37213603, 2023).
cyst (1 paper, 2016). A sac-like closed membranous structure that may be empty or contain fluid or amorphous material. "Thus, all the caspase genes examined were enhanced in the AQP11(−/−) kidney before (at two weeks) and after (at eight weeks) cyst formation with remarkably higher expressions of Casp1, Casp4 and Casp12." (PMID 27916883, 2016).
diabetes (1 paper, 2022). "Associated cardiovascular diseases include diabetes (PDLIM5, HDAC4, and TLE1), cardiac development (PDLIM5) and myocardial aging (CASP12), hypertension (PFKP and TAB2), and intracerebral and intraventricular bleeding (RUNX1) and stroke (AXIN2)." (PMID 36620623, 2022).
lymph node metastasis (1 paper, 2019). "The results showed that CASP12 expression was significantly associated with differentiation, lymph node metastasis, tumor size, FIGO staging and clinical outcomes (P<0.05), but not with age, HPV types and pathological types (P>0.05)." (PMID 31804677, 2019). "In the present study, there were statistically significant differences between the groups of CASP12 mRNA with high and low expression in terms of differentiation, lymph node metastasis, tumor size, FIGO staging and clinical outcomes." (PMID 31804677, 2019). "There were statistically significant differences between CASP12 groups with high and low expression in terms of differentiation, lymph node metastasis, tumor size, FIGO staging, and clinical outcomes (P<0.05), but not in terms of age, HPV types and pathological types (P>0.05)." (PMID 31804677, 2019).
malaria (1 paper, 2022). Malaria is a serious and sometimes fatal disease caused by a parasite that commonly infects a certain type of mosquito which feeds on humans. "Similarly, we observed a transcriptional increase of CASP12, encoding caspase 12, which was shown to suppress immune responses in a mouse malaria model of infection." (PMID 36036514, 2022).
psoriasis (1 paper, 2019). An autoimmune condition characterized by red, well-delineated plaques with silvery scales that are usually on the extensor surfaces and scalp. "We found that the interaction of CASP10 - CASP1, CASP10- CASP3, CASP10- CASP4, CASP10- CASP9, CASP10- CASP12, CASP8 - CASP3, CASP8 - CASP4, and CASP1 - CASP12 is important for the risk of psoriasis." (PMID 30906769, 2019).
sarcopenia (1 paper, 2023). Progressive decline in muscle mass due to aging which results in decreased functional capacity of muscles. "Previous studies also indicate the associations of CASP-12 with sarcopenia in older population." (PMID 37667196, 2023).
viral myocarditis (1 paper, 2025). Myocarditis that is caused by an infection with a viral agent. "Ultimately, four overlapping features, namely, B2M, C3, CFB, and CASP12, were selected as potential biomarkers for viral myocarditis using both algorithms." (PMID 40230577, 2025).
infection (8 papers, 2016 to 2024). The state of being infected such as from the introduction of a foreign agent such as serum, vaccine, antigenic substance or organism. "Casp12 has an anti-inflammatory function during infection, which expressed in cancer cells implies the simultaneous presence of some selective benefit for cancer pathogenesis." (PMID 28380444, 2017).
cancer (5 papers, 2015 to 2022). A tumor composed of atypical neoplastic, often pleomorphic cells that invade other tissues. "In cancer pathology, the inflammatory microenvironment and oncogenic mutations often induce chronic inflammation, and CASP12 induction is associated with cancer cell invasion after pre-inflammatory stimulation." (PMID 36452159, 2022). "Induction of Casp12 is implicated in cancer cell invasion after the proinflammation stimuli." (PMID 33924755, 2021). "The alternative activated pathway of NF-κB is induced by Casp12 might be implicated in MMP-9-mediated carcinoma cell invasion." (PMID 28380444, 2017). "Thus, induction of Casp12/NF-κB signaling might be associated with MMP-9-induced aggressive metastasis in carcinoma cell." (PMID 28380444, 2017). "Recent studies indicated induction of Casp12 in the pathological condition included kidney cells and cancer cells." (PMID 33924755, 2021). "Therefore, CASP12 role in inflammation is widely known; however, there are currently few studies on CASP12 in cancers." (PMID 31804677, 2019). "Under certain pathologic conditions, Casp12 is expressed in human tissues, including proximal tubule cells of kidney and cancers such as Hep-J5 cells, multiple myeloma, gastrointestinal stromal tumor, glioblastoma and NPC cells, suggesting a selective advantage in cancer cells." (PMID 28380444, 2017). "The importance of Casp12 in hardwiring NF-κB signal transduction pathways to the regulation of MMP-9 gene may be a therapeutic target for carcinoma." (PMID 28380444, 2017). "Moreover, downregulation of Casp12 impairs the cancer cell invasion via inactivation of NF-κB." (PMID 33924755, 2021). "However, the physiological function of Casp12 presented in cancer cells is still unclear." (PMID 28380444, 2017). "However, the physiological function of Casp12 in cancer cells is still unclear." (PMID 28380444, 2017).
tumor (4 papers, 2013 to 2023). "Consistently, the scRNA-seq analysis revealed that the expression levels of Perk, Eif2a, Chop, and Casp12 were significantly upregulated in the T1 tumor cluster from Ero1aKO tumors compared with WT counterparts, suggesting they were more susceptible to death." (PMID 37769655, 2023).
CASP12 also shares sentences with these, for which no sentence is quoted: breast carcinoma (2 papers); Skin Cutaneous Melanoma (2); cardiovascular diseases (1); Hypertension (1); lung adenocarcinoma (1); Lung squamous cell carcinoma (1); metastatic melanoma (1); nevus (1); ovarian serous cystadenocarcinoma (1); prostate adenocarcinoma (1); rheumatoid arthritis (1); scrapie (1); Stroke (1); systemic lupus erythematosus (1); thymoma (1); uterine carcinosarcoma (1).